STAT3 (signal transducer and activator of transcription 3)
Diseases named in the same sentence as STAT3 in open-access papers (continued):
Sharing a sentence is not in itself a finding about the gene and the disease.
breast cancer (continued). "It is therefore not surprising that the ectopic expression of IL-6 or treatment with recombinant IL-6 in ER+ breast cancer cells significantly increases the expression of EMT-related genes through STAT3, leading to increases in tumor cell proliferation in orthotopic xenograft models." (PMID 32023849, 2020). "In breast cancer, adipocytes from the tumor microenvironment could produce IL-6, which then activates STAT3 in cancer cells and induces the EMT phenotype by increasing the expression of PLOD2, which is important for matrix remodeling." (PMID 33322216, 2020). "In addition, we observed that silencing STAT3 blocked the leptin-induced increase in PAI-1 in breast cancer cells." (PMID 33371368, 2020). "Moreover, a recent study reported that circulating fatty acid-binding protein released by adipose tissue (A-FABP or FABP4) promotes breast cancer stemness by activating the IL-6/STAT3/ALDH1 pathway." (PMID 32913185, 2020). "This inhibitor suppresses the activity ofSTAT-3 luciferase and STAT-3 DNA binding in breast cancer." (PMID 32167126, 2020). "As IKKα and STAT3 co-localized in human breast cancer patient tissues as well as human breast cancer cell lines, we speculated that STAT3 could stabilize IKKα protein through physical interaction." (PMID 33396715, 2020). "Suppression of Stat3 expression induced Fas-mediated breast cancer cells apoptosis." (PMID 32565740, 2020). "STAT3, a downstream effector of several receptor tyrosine kinases (RTKs) commonly activated by growth factors and cytokines, is persistently activated in all breast cancer subtypes." (PMID 32391382, 2020). "Moreover, downregulation of PIWIL2 decreased proliferation and survival of breast cancer stem cells through a decrease in the protein levels of STAT3, BCL-XL and Cyclin D1." (PMID 32357464, 2020). "In addition, parthenolide inhibits STAT3 activation and exerts anticancer effects in breast cancer, gastric cancer, prostate cancer and colon cancer cells." (PMID 32312954, 2020). "OSM has also been shown to induce IL-6 in a STAT3-dependent manner in ER- breast cancer cells." (PMID 32023849, 2020). "Therefore, new drug discoveries in reverence to STAT3 inhibition would improve consequences of breast cancer treatment qualitatively, and more importantly, for both ER+ and ER- breast cancer." (PMID 33013353, 2020). "Similarly, TAM-secreted IL-6 activates the STAT3 pathway in breast cancer to upregulate TGF-β1 and hypoxia inducible factor 1-alpha (HIF-1α) gene expression during chemotherapy-induced apoptosis." (PMID 32326073, 2020). "In our study, we found that targeting CDK7 increased the toxic effect of tamoxifen in sensitive and resistant breast cancer cells as well as in vivo models by targeting important proteins, such as ER and MYC, and essential pathways in breast cancer progression (STAT3 and β-catenin)." (PMID 32340192, 2020). "STAT3 expression was upregulated in DOX-R breast cancer stem cells as shown by Western blot." (PMID 32668603, 2020). "The incubation with Faecalibacterium prausnitzii supernatant could inhibit the secretion of IL-6 and the phosphorylation of JAK2/STAT3 in breast cancer cell line MCF-7." (PMID 32272885, 2020). "Thus, our results suggest the potential for pharmacologic inhibition of STAT3 in CD103+ cDC1s as a novel treatment strategy for the immunotherapy of breast cancer." (PMID 31947933, 2020). "Our results may bring insights to the HIF‐1α/STAT3 interaction in breast cancers and suggest sanguinarine as a promising candidate for HIF‐α/STAT3 inhibition." (PMID 32065498, 2020). "Importantly, we firstly reported the inhibitive effects of Faecalibacterium prausnitzii for the growth of breast cancer cells through IL-6/STAT3 pathway." (PMID 32272885, 2020). "Notably, the aberrant regulation of STAT3 is reported in a range of human cancers including breast cancer, making it a potential therapeutic target." (PMID 32503225, 2020).
breast cancer (continued). "After co-culturing human breast cancer cell lines (MDA-MB-231, MDA-MB-468, and MCF-7) with PMA-induced human monocyte THP-1 cells for 48 h, we found that either STAT3 knockdown or JAG1 knockdown in breast cancer cells reduced the relative mRNA levels of CD206 and CD163 in THP-1 derived macrophages." (PMID 32943090, 2020). "Furthermore, it is consistent with the findings that MNX1-AS1 upregulated proliferation and invasion in breast cancer by activating AKT/mTOR pathway which was overlapped with JAK/Stat3 signaling pathway." (PMID 32754442, 2020). "However, STAT3 has mainly been found in basal-like breast cancer cells, CD44+ CD24–, in which the secretion of IL-6 increases the level of pSTAT3 through an autocrine growth regulator loop." (PMID 32850390, 2020). "Our study has also established that phosphorylation of PLSCR1 Tyr 69/74 plays an instrumental role in the proliferation and stemness of breast cancer cells by promoting its nuclear translocation, interaction with STAT3 and subsequent binding to the STAT1 promoter." (PMID 32292520, 2020). "Also, the comprehensive molecular mechanism of inhibition of STAT3 activation by PSD-A has been disclosed for the first time in breast cancer cells." (PMID 33013353, 2020). "Additionally, SB203580, a commercial p38 inhibitor, stimulated STAT3 activation and improved autophagic events rate in breast cancer cells, displaying the role of the MAPK signaling pathway in interplay between apoptosis and autophagy." (PMID 33013353, 2020). "Moreover, IL-6 or leptin can increase procollagen-lysine, 2-oxoglutarate 5-dioxygenase 2 (PLOD2) expression in breast cancer cells through the activation of the JAK/STAT3 and the AKT signalling pathway." (PMID 32033341, 2020). "It has been noted that both Wnt/β-catenin and STAT3 signaling pathways are closely related to tumors and have synergism with the occurrence and progression of tumor, in which STAT3 upregulates the protein expression and transcriptional activity of β-catenin in breast cancer." (PMID 33488528, 2020). "Constitutive STAT3 activation in breast cancer cells induces EMT and CSC properties." (PMID 32391382, 2020). "In addition, S1P binding to S1P1 has also been shown to promote STAT3 activation, which is pro-tumorigenic in breast cancer." (PMID 32260399, 2020). "Using Bayesian inference, a mathematic framework, researchers have found that combination therapy targeting mTOR and STAT3 may be the best therapeutic target in breast cancer." (PMID 32111215, 2020). "Furthermore, resistin is found to promote EMT and CSC-like properties in breast cancer cells through a TLR4/NF-κB/STAT3 signaling pathway." (PMID 33123472, 2020). "Therefore, the inhibition of abnormally elevated STAT3 activity or expression represents a rational therapeutic modality for malignancies, including breast cancer." (PMID 33053804, 2020). "Importantly, the abundance of Faecalibacterium was decreased in breast cancer women and we also found that Faecalibacterium prausnitzii supernatant can suppress the growth of breast cancer cells through the inhibition of IL-6/STAT3 pathway." (PMID 32272885, 2020). "While studies have confirmed that the loss of LIFR:STAT3 signaling is associated with reduced breast cancer patient survival, to date, there are no clinical studies that have rigorously tested these cytokines and their receptors in the oncology setting." (PMID 32023849, 2020). "Here, we examined whether STAT3 controlled the efficacy of CD103+ cDC1s used as a cell-based vaccine for murine breast cancer, a cancer type that is refractory to immunotherapy." (PMID 31947933, 2020). "Hence, as a tumour suppressor, STAT5 activation can counteract the oncologic effects of STAT3, which is more commonly constitutively activated in breast cancer compared to STAT5." (PMID 32872372, 2020). "Thus, breaking the STAT3-IKKα alliance can be an alternative therapeutic strategy for the treatment of breast cancer." (PMID 33396715, 2020).
breast cancer (continued). "Taken together, leptin mediated crosstalk between adipocytes and breast cancer cells, which further activated STAT3 not only directly to facilitate PAI-1 expression but also to indirectly affect PAI-1 by repressing miR-34a, thus promoting PAI-1-related EMT to strengthen breast cancer metastasis." (PMID 33371368, 2020). "One of the mechanisms through which leptin causes breast cancer progression is the regulation of breast cancer stem cell (CSC) activity by modulating the many signalling pathways (i.e., Notch, Wnt, mTOR, STAT3, HER2/Erb, and IGF pathways) and transcription factors (i.e., HIF-1 and NFκB)." (PMID 32033341, 2020). "Furthermore, we obtained evidence that adipocytes secreted leptin to activate OBR in breast cancer cells, which phosphorylated STAT3 to promote the transcription of PAI-1 and repress the expression of miR-34a as the negative regulator of PAI-1." (PMID 33371368, 2020). "Moreover, mitochondrial STAT3 contributes to the Ras-dependent malignant transformation of Barrett’s epithelial cells and promotes the growth of breast cancer cells." (PMID 33003453, 2020). "In breast cancer, promotion of the IL-10 induced immunosuppressive Treg phenotype depends on the stage of cancer, and during its formation other mediators are involved in addition to activated STAT3." (PMID 32488850, 2020). "Treatment with STAT3 inhibitors alone or combined with other clinical therapeutic drugs may provide more promising effects on suppressing or reversing chemoresistance in breast cancer." (PMID 32111215, 2020). "Additionally, leptin favors breast cancer progression by inducing cellular proliferation by binding to its receptor followed by downstream signaling through NFκB, STAT3, ERK1/ERK2, and phosphoinositide-3-kinase (PI3K) pathways." (PMID 32257945, 2020). "Therefore, STAT3 remains to be a strong clinical target for breast cancer prevention and therapy, which is worth continuous research." (PMID 32111215, 2020). "Based on these findings, we assumed that lncRNAs in breast cancer cells may regulate the Notch signaling pathway via STAT3-mediated transcription modulation of Jagged1." (PMID 32943090, 2020). "Activation of STAT3 pathway was reported in a variety of malignancies including breast cancer." (PMID 32649314, 2020). "Moreover, in a large cohort of patients with early breast cancer, a correlation between STAT3 and PD-L1 at both the RNA and protein levels was described." (PMID 32727138, 2020). "Constitutive activation of STAT3 signaling is observed in 50–60% of breast cancer events." (PMID 32878084, 2020). "In addition to affecting tumor cells directly, 27-HC induced endothelial to mesenchymal transition in endothelial cell lines via STAT3 signaling and aided breast cancer cell migration." (PMID 33604295, 2020). "Specifically, leptin is thought to promote breast cancer through the activation of Janus kinase 2/Signal Transducers and Activators of Transcription 3 (Jak2/Stat3), mitogen-activated protein kinase (MAPK) and Phosphatidylinositol-3-kinase/Protein kinase B (PI3K-AKT)." (PMID 33019728, 2020). "Inflammation and STAT3 signalling in adipose tissue, therefore, work together to create an environment that promotes tumour proliferation and survival through metabolic reprogramming in breast cancer." (PMID 32331320, 2020). "In breast cancer, most STAT3 pathway inhibitors are still in the preclinical phase of development, but represent a promising category of therapeutics due to the role of STAT3 in promoting cancer cell plasticity." (PMID 32391382, 2020). "In addition, small molecule inhibitors targeting STAT3 activation have been found to be efficient for therapeutic treatment of breast cancer." (PMID 32111215, 2020). "In addition, the p-STAT5, p-AKT and p-STAT3 pathways also have a certain degree of activation, thereby promoting breast cancer cell proliferation and migration ability." (PMID 32322171, 2020).
breast cancer (continued). "In this study, we found that Faecalibacterium prausnitzii could inhibit the secretion of IL-6 and the phosphorylation of JAK2/STAT3 in breast cancer cells." (PMID 32272885, 2020). "Notably, the leptin-induced increase in PAI-1 in breast cancer cells was significantly blocked by silencing STAT3." (PMID 33371368, 2020). "Studies have also shown the growth of breast cancer cells is inhibited by STAT3 inhibitors." (PMID 32340377, 2020). "Additionally, STAT3, FAK, and BCAR1 are relevant PTK6 substrates in breast cancer, and PTK6 protects breast cancer cells from autophagic cell death induced by loss of anchorage, suggesting that PTK6 can inhibit autophagic processes." (PMID 33109128, 2020). "Then the phosphorylated Stat3 activated the progression of breast cancer in vitro and in vivo." (PMID 32754442, 2020). "Furthermore, arctigenin-induced depletion of GM-CSF and TSLP inhibited STAT3 phosphorylation and β-catenin signaling resulting in decreased proliferation, invasion and stemness of breast cancer cells in vitro and in vivo." (PMID 32887217, 2020). "In this review, we examine the central role played by the crosstalk between the transcriptional and mitochondrial roles of STAT3 to promote survival and further oncogenesis within the tumour microenvironment with a particular focus on adipose-breast cancer interactions." (PMID 32331320, 2020). "Similarly, STAT3 inhibition diminished the mammary carcinoma incidence and decreased the tumor size and aggressiveness; also, minor ObR expression and high levels of miR-200c and Cdh1 were observed in tumor tissue." (PMID 33334030, 2020). "Based on the observation of the co-expression and co-localization of IKKα and STAT3, we speculated that IKKα might also play a role in the progression of human breast carcinoma, as STAT3 does." (PMID 33396715, 2020). "Leptin could also promote proliferation in breast cancer cells in vitro via steroid receptor coactivator (SRC)-1/STAT3 signaling pathway." (PMID 31500658, 2019). "In addition, activated STAT3 was reported to affect the resistance of anti-breast cancer drugs like Paclitaxel6 and Adriamycin7." (PMID 31375715, 2019). "We next sought to determine whether STAT3 could reverse the effects of SIRT4 on the response of breast cancer cells to tamoxifen." (PMID 31573734, 2019). "Our findings provide evidence for STAT3-mediated regulation of PD-L1 in vitro and impact on accumulation of pro-tumoral macrophages and other immune cell subpopulations in an in vivo murine mammary tumor model." (PMID 31581535, 2019). "siRNA knockdown of STAT3 blocked macrophage-induced expression of breast cancer proliferative genes cyclin D1 and c-Myc, and of cytokines IL-6, CCL5, and MCP-1, demonstrating the essential role of STAT3 expression in conditioned macrophage-induced alteration of gene expression." (PMID 30736340, 2019). "We conclude that more than one flavonoid compound could act to suppress the functional activity of p-STAT3 in MDA-MB-231 breast cancer cells, with varying degree of relative efficacy." (PMID 31491838, 2019). "In addition, intrinsic kinases such as EGFR (epidermal growth factor receptor) and VEGFR (vascular endothelial growth factor receptor) can mediate aberrant phosphorylation of STAT3 in breast cancer." (PMID 31058868, 2019). "Moreover, SRC kinase has been proposed as a key upstream protein for persistent STAT3 activation, which drives the robust outgrowth of breast cancer cells." (PMID 31324052, 2019). "Finally, Knock down of STAT3 in the multidrug resistant breast cancer, SK-BR-3/EPR, cell line inhibited cell invasion and downregulated MMP-9 in these cells." (PMID 31456939, 2019). "Persistent activation of STAT3 has been described in several cancers including breast cancer." (PMID 31456939, 2019). "As STAT3 may contribute to the migration of breast cancer cells, we aimed to ascertain its involvement in the migratory features of TNBC cells mediated by GPER." (PMID 30728047, 2019).
breast cancer (continued). "Further evidence for STAT3 as a tumor suppressor has been reported in lung, colon, thyroid, liver, skin, neck, nasopharynx, rectum, salivary gland and breast cancers but the mechanisms remain to be investigated." (PMID 31557897, 2019). "Therefore, IL-6 promotes the invasion, metastasis, and angiogenesis of breast cancer mainly by activating JAK/STAT3 signaling pathway." (PMID 31500658, 2019). "Thus, the expression of STAT3/p-STAT3 plays a clinicopathological and prognostic role in the diagnosis and treatment of Chinese breast cancer patients." (PMID 31375715, 2019). "Furthermore, PD-L1 expression in the SKBR3 breast cancer cell line stably transfected with a constitutively active STAT3 construct was examined." (PMID 31581535, 2019). "Moreover, recent studies have confirmed that Stat3 is activated in breast cancer, and its overexpression was closely related to the development of breast cancer." (PMID 31649548, 2019). "In this study, we examined whether the cyclohexene-truncated bicyclic lactone analogues SG-1709 and SG-1721 derived from natural GL can inhibit tumor growth by effectively blocking the STAT3 signaling pathway in vitro and in vivo in breast cancers." (PMID 31058868, 2019). "Our study provides evidence that human-adipocyte CM can induce EMT in breast cancer cells through the IL-6/STAT3 signalling pathway, perturbation of IL-6/STAT3 signalling with niclosamide inhibit STAT3 phosphorylation and reverse adipocyte-induced EMT in breast cancer cells." (PMID 31383893, 2019). "Considering the effects of Stat3 in breast cancer, we hypothesized that Pec., a potent inhibitor of Stat3, might be effective in the treatment of patients with breast cancer." (PMID 31649548, 2019). "A study investigating the combined treatment of curcumin and β-interferon (IFN-β)/retinoic acid (RA) showed that curcumin synergistically increases the efficacy of β-interferon (IFN-β)/retinoic acid (RA) in breast cancer cells by upregulating GRIM-19 via Stat3-independent and –dependent pathways." (PMID 31618928, 2019). "Notably, the crosstalk between the Notch-1, Wnt/β-catenin, and STAT3 signaling pathways has been reported in breast cancers and breast cancer stem cells." (PMID 31357721, 2019). "In addition, our research found a higher STAT3 or p-STAT3 expression level in breast cancer cells which kept the characteristics of rapid proliferation, less differentiation and lymphatic metastasis." (PMID 31375715, 2019). "What’s more, increasing evidences elucidated that blockade of Stat3 by inhibitors could trigger apoptosis and inhibit tumor growth in breast cancer." (PMID 31649548, 2019). "A different proliferative effect of leptin in breast cancer cells involves the leptin mediated upregulation of human telomerase reverse transcriptase (hTERT) activity and expression in a dose-dependent fashion also involving STAT3 phosphorylation." (PMID 31380268, 2019). "Therefore, immunofluorescence was used to detect the localization of STAT3 in breast cancer cells after SIRT4 overexpression or depletion." (PMID 31573734, 2019). "Moreover, it is known that, in the context of breast cancer, STAT3 activity can be modulated through STAT5 activity, and their combined functions can have an impact on breast cancer progression." (PMID 31247937, 2019). "A higher STAT3/p-STAT3 expression level was observed in breast cancer tissue than in normal tissues, which aroused our interest to study the relationships between STAT3/p-STAT3 expression level and the occurrence, development and metastasis of breast cancer in Chinese women." (PMID 31375715, 2019). "Interestingly, BITC treatment can block leptin-induced breast cancer growth by directly inhibiting leptin-mediated Stat3 activation." (PMID 31618928, 2019). "Importantly, inhibition of p-STAT3 was accompanied by a reduction in IL-6 secretion, hence depriving breast cancer cells of this critical growth-promoting factor." (PMID 31491838, 2019).